CCND1 (cyclin D1)
Diseases named in the same sentence as CCND1 in open-access papers (continued):
Sharing a sentence is not in itself a finding about the gene and the disease.
glioma (continued). "In addition, we investigated the potential biological process through which BACE2 promotes glioma malignant development and evaluated the expression levels of some key regulators of the cell cycle, including CDK2, CDK4, cyclin D1, p21 and p27." (PMID 31856384, 2020). "Besides, FOXO1 knockdown elevated protein levels of P‐PI3K, P‐AKT, CDK4, CCND1, c‐JUN, N‐cadherin and vimentin in glioma cells." (PMID 32902145, 2020). "Furthermore, knockdown of endogenous β-catenin levels significantly attenuated IGF-1-induced cyclin D1 and cell growth, suggesting that IGF-1 induced β-catenin signaling activation in glioma cells." (PMID 31805126, 2019). "In contrast, the expression of Ki67 and STAT3 target genes (CCND1 and SOX2) were significantly reduced in the MH2-treated xenografts, indicating a therapeutic effect of TAT-MH2-NLS protein for glioma." (PMID 29950561, 2018). "When we referred to our other pediatric brain tumor datasets, including high-grade gliomas (HGGs), atypical teratoid/rhabdoid tumors (AT/RTs), and medulloblastoma (MBs), we found that CCND1 was also overexpressed in HGGs and AT/RTs (data not shown)." (PMID 29416789, 2018). "Protein expression of Cyclin D1, p-AKT and AKT in rat glioma C6 cells was detected by Western Blot." (PMID 29351283, 2018). "The expression of miR-17 was significantly lower, whereas the expression of Cyclin D1 was significantly higher in glioma C6 cells compared to normal brain tissue." (PMID 29351283, 2018). "Protein expression of Cyclin D1, p-AKT and AKT in glioma C6 cells was detected by Western Blot." (PMID 29351283, 2018). "In the PPI network, we also found that CCND1 had interaction with THBS1, suggesting that CCND1 could be involved in regulating proliferation and invasion of glioma via interacting with THBS1." (PMID 27716259, 2016). "We next examined the noise-induced qualitative changes in cyclin D1 and GFAP in glioma cells." (PMID 27515956, 2016). "In serum-starved glioma cells, PACAP treatment decreased the cyclin D1 levels." (PMID 25426938, 2014). "Moreover, we demonstrated that upregulation of miR-195 in glioma cells led to the downregulation of phosphorylated pRb and proliferative marker PCNA through downregulation of cyclin D1 and cyclin E1 via directly targeting the 3′-UTR of cyclin D1 and cyclin E1." (PMID 23383003, 2013). "However, flavopiridola, an available cyclin D1 inhibitor reserved the accelerated cell growth and the increased phosphorylation of pBb induced by CDKN2A knockdown in low-grade glioma cells." (PMID 21843312, 2011). "Furthermore, in glioma, PC3/Tis21/BTG2 enhances apoptosis rates while simultaneously decreasing the migration and invasion of cancerous cells, and lowering the levels of cyclin D1." (PMID 42080092, 2026). "Notably, adding CHIR99021 (10 μm, for 3 days) to the control medium significantly induced β‐catenin and Met expression in glioma cells but did not affect the expression of c‐Myc, cyclin D1 and CD44 (data not shown)." (PMID 37410396, 2023). "In glioma, miR-34a suppresses cell cycle progression and proliferation of glioma cells through direct inhibition of the expression of MET receptor tyrosine kinases (c-MET RTK), Notch-1, Notch-2, cyclin-dependent kinase 6 (CDK6), cyclin 1 (CCND1), and silent information regulator 1 (SIRT1)." (PMID 35922753, 2022). "In addition, our findings demonstrated that FOXN3 over-expression triggered an obvious reduction in PCNA, CCND1, MMP9 and Vimentin expression levels in glioma cells, whereas FOXN3 ablation elicited a remarkable elevation in PCNA, CCND1, MMP9 and Vimentin expression levels." (PMID 34511432, 2021).
glioma (continued). "We wondered whether CCND1 and RAP1B could affect the PI3K/AKT/mTOR signaling pathway in glioma." (PMID 33676540, 2021). "Moreover, cell cycle perturbation in Parkin-expressing glioma was accompanied by a considerable reduction in cyclin D1 levels, but not in cyclin E." (PMID 34360883, 2021). "Besides, Western blotting revealed that miR‐5188 inhibition led to reduced protein levels of P‐PI3K, P‐AKT, CCND1, CDK4 and c‐JUN, but increased protein levels of FOXO1 in glioma cells with SP1 overexpression, suggesting that miR‐5188 was enhanced by SP1 through the PI3K/AKT pathway." (PMID 32902145, 2020). "Moreover, restoration of miR-124a could inhibit glioma cell proliferation and invasion through miR-124a blocking the expression of the IQGAP1 gene and downstream β-catenin and cyclin D1 and PIM1 in astrocytoma cancer cells." (PMID 29138748, 2017). "CEBPB might act in glioma by regulating CCL2, CCND1, THBS1, THBS2, SMAD5, SMAD6, TGFBR2, and TCF12." (PMID 27716259, 2016). "In basal conditions, we show that the inhibition of EPOR affects the cell cycle of glioma cells with a G2/M arrest accompanied with an increase in the cyclin B1 expression, an indicator of G2/M arrest but not that of cyclin D1 expression, a critical mediator of G1 to S phase progression." (PMID 25544764, 2015). "Interestingly, the protein level of cyclin D1, a CDK regulator important for regulating the G1/S transition, was downregulated in LN18 and T98G glioma cells transfected with miR-329 mimic, but increased in the cells transfected with miR-329 inhibitor, compared with control cells." (PMID 23866847, 2013). "This interaction stabilized FOXM1 protein levels and sequentially induced the expression of a series of oncogenes, such as MMP-2, VEGF, Chk2 and cyclin D1, which suggests that in addition to metabolic functions, PHGDH may have other biological roles in glioma tumorigenesis." (PMID 23229761, 2013). "However, unlike in many other cancers, CCND1 is not differentially expressed in different grades and types of brain tumours, and TCGA outcome data do not show a difference in survival between patients with gliomas expressing low or high CCND1 levels." (PMID 29720725, 2018). "Moreover, to uncover the potential molecular mechanisms by which TAGLN2 promote glioma development, we detect the expression change of FoxM1, an oncogenic transcriptional factor that regulates some key mediators of cell cycle progression, including CDK2, cyclin B1, cyclin D1, p21 and p27." (PMID 29110682, 2017). "Notably, basal cyclin D1 levels were higher in CD133+ cells than matched CD133− cells, whereas cyclin D2 and cyclin E levels were higher in CD133− cells, suggesting that cyclin D1, but not cyclins D2 or E, is critical for the G1/S transition in CD133+ glioma cells." (PMID 19020659, 2008). "As predicted, re-introduction of the Cyclin D1 or Cyclin E1 ORF (without 3′UTR) in miR-195-transfected cells abrogated, at least partially, the miR-195-mediated glioma cell growth arrest, as analyzed by the BrdUrd incorporation assay." (PMID 23383003, 2013). "Compared to the negative control, the expression of cyclin D1 was significantly reduced after GBE1 knockdown, which further proved that GBE1 knockdown could transform glioma cells into a resting state and inhibit proliferation." (PMID 36900384, 2023).
pancreatic cancer (199 papers, 2002 to 2026). "Overexpression of c‐myc in pancreatic cancer caused enhancement of sensitivity to cisplatin‐induced cell death due to inhibition of cyclin D1 expression." (PMID 40051490, 2025). "Cells overexpressing cyclin D1 are susceptible to poor prognosis and resistance to chemotherapy, especially in pancreatic cancer." (PMID 40051490, 2025). "Another example is the molecules miR-15a and miR-16-1, whose dysregulation allows prostate and pancreatic cancers to develop by influencing the signaling pathways associated with CCND1 (cyclin D1), WNT3A and BCL2." (PMID 35269947, 2022). "In pancreatic carcinoma cells, transient overexpression of the FL isoform induced cell cycle-related genes (encoding c-myc and cyclin D1) in cooperation with β-catenin." (PMID 35938168, 2022). "STAT3 is a central transcription factor in the progression of pancreatic cancer, which can promote the transcription of multiple genes encoding proliferation-related proteins, such as Cyclin D1." (PMID 34858184, 2021). "Previous studies have also demonstrated that Cyclin D1 overexpression is closely associated with the poor prognosis in post-operative pancreatic cancer patients." (PMID 34412631, 2021). "Overexpression of CST1 was also correlated with malignancy-associated proteins such as PCNA, cyclin D1, cyclin A2 and cyclin E in pancreatic cancer cell line." (PMID 26569312, 2015). "Previous studies have shown that inhibition of GSK3β reduced the proliferation and survival of pancreatic cancer cells, which was associated with decreased cyclin D1 expression, Rb phosphorylation and secretion of matrix metalloproteinase-2 (MMP-2)." (PMID 26213494, 2015). "LRH-1 expression is elevated in pancreatic cancer and promotes pancreatic cancer cell growth through stimulation of cyclin D1, cyclin E1 and c-Myc, while genome-wide association studies implicate mutations in the LRH-1 gene in pancreatic ductal adenocarcinoma." (PMID 24049078, 2013). "We also demonstrate that the gene encoding cyclin D1 is a direct transcriptional target of Six1 in pancreatic cancer cells." (PMID 23527134, 2013). "We also show that the gene encoding cyclin D1 is a direct transcriptional target of Six1 in pancreatic cancer cells." (PMID 23527134, 2013). "Cyclin D1 is an important regulatory protein required in cell cycle progression, and overexpression has been associated with a poor prognosis in patients with pancreatic cancer." (PMID 22570653, 2012). "Additional mechanisms that contribute to cisplatin resistance in pancreatic cancer include overexpression of cyclin D1 and multidrug resistance-associated proteins." (PMID 22053213, 2011). "In pancreatic cancer, overexpression of cyclin D1 is associated with increased aggressiveness of these tumours." (PMID 11953870, 2002). "Furthermore, overexpression of cyclin D1 mRNA is associated with a decreased survival rate in pancreatic cancer, similar to its immunostaining results." (PMID 40051490, 2025). "Further, NR5A2 expression is elevated in pancreatic cancer andpromotes pancreatic cancer cell growth through stimulation of cyclin D1, cyclin E1 and c-Myc, while genome-wide association studies implicate mutations in the NR5A2 gene in pancreatic ductal adenocarcinoma." (PMID 25514243, 2014). "Treatment of pancreatic cancer BxPc-3 and Panc-1 cells with α-mangostin resulted in loss of cell viability, accompanied by enhanced cell apoptosis, cell cycle arrest at G1 phase, and decrease of cyclin-D1." (PMID 24812621, 2014). "Increasing levels of immunoreactivity to Fascin, Ki67, Her-2, Cyclin D1, Cox-2 were associated with mPanIN progression to invasive cancer as they are in humans, which further validated the similarities between the invasive pancreatic tumors found in our models and human PDA." (PMID 22113502, 2011).
pancreatic cancer (continued). "ZC3HAV1, a PARP family enzyme, has been shown in pancreatic cancer to regulate cell cycle progression by modulating cyclin D1 and CDK2, and to bind KRAS, enhancing its expression and activating ERK signalling to promote proliferation and metastasis." (PMID 41596441, 2026). "This narrative review explores the potential of proliferative markers, namely Ki‐67, PCNA, PHH3, and Cyclin D1, as predictive and prognostic tools in pancreatic cancer chemotherapy." (PMID 40051490, 2025). "In conclusion, proliferative markers including Ki‐67, PCNA, PHH3 and Cyclin D1 have demonstrated promise as predictive and prognostic biomarkers in the context of pancreatic cancer chemotherapy." (PMID 40051490, 2025). "Proliferative markers, such as Ki‐67, PCNA, PHH3, and Cyclin D1, have been investigated for their potential use as predictive and prognostic biomarkers in pancreatic cancer chemotherapy." (PMID 40051490, 2025). "The incorporation of proliferative markers like Ki‐67, PCNA, and Cyclin D1 into treatment decision‐making for pancreatic cancer is promising but comes with significant limitations that restrict their current clinical utility." (PMID 40051490, 2025). "Cyclin D1, frequently overexpressed in pancreatic cancers, correlates with increased proliferation and apoptosis resistance." (PMID 40051490, 2025). "Cyclin D1 has also been investigated as a potential biomarker for predicting chemotherapy response in pancreatic cancer." (PMID 40051490, 2025). "Cyclin D1, a crucial cell cycle regulator, is overexpressed in pancreatic cancer tissues and signals increased cell proliferation." (PMID 40051490, 2025). "Ki‐67, PCNA, and Cyclin D1 offer valuable insights into pancreatic cancer biology and PanIN progression." (PMID 40051490, 2025). "Previous studies have reported that MA significantly enhances tumor necrosis factor-α-induced inhibition of pancreatic cancer cell proliferation by suppressing cyclin D1, COX-2, and c-Myc expression levels." (PMID 39624845, 2024). "The expression of key cell cycle components increased with cell cycle arrest, and Cyclin D1 was suppressed in pancreatic cancer cells." (PMID 38690008, 2024). "It has been confirmed that CCND1 can be regulated by miR-193a-3p to inhibit the rapid growth and metastasis of pancreatic cancer." (PMID 38787178, 2024). "A similar adaptive overexpression of cyclin D1 was observed upon treatment with palbociclib in pancreatic cancer cells." (PMID 39123441, 2024). "This microRNA prevents invasion and metastasis by reducing the cyclin D1, C-myc, and β catenin expression in pancreatic cancer cells." (PMID 38559560, 2024). "In the pancreatic cancer model, TLR7 signaling through STAT3 results in loss of PTEN, p16, and cyclin D1, which leads to tumor development." (PMID 38850110, 2024). "The aberrant activation of the cyclin-dependent kinase 4/cyclin D1 pathway is reported frequently in pancreatic cancer due to the overexpression of D-type cyclin proteins." (PMID 39123441, 2024). "Integrated data mining analysis identified the PVT1/miR-20b/CCND1 axis as a promising pathway-related ceRNA axis in the progression of pancreatic cancer." (PMID 37628628, 2023). "We also tested the therapeutic effect of CDK4/6 inhibitors in SEMA6C-low pancreatic cancer, which exhibited increased cyclin D1 expression." (PMID 35269749, 2022). "Beta-catenin and one of its main downstream effectors, cyclin D1, are also augmented in our study, being strongly correlated with a poorer prognosis in patients with pancreatic cancer." (PMID 35448172, 2022). "Our study has provided a direct association between pancreatic cancer survival and the overexpression of EGFR, beta-catenin, cyclin D1, CDK4, and ErbB2." (PMID 35448172, 2022). "The aim of this article is to analyze the tissue expression of EGFR, Beta catenin, cyclin D1, CDK4, and ErbB2 in pancreatic cancer in order to find their association with the mortality and survival of patients with this tumor." (PMID 35448172, 2022).
pancreatic cancer (continued). "Further pharmacological study demonstrated that the expression level of Cyclin D1 was down-regulated by the treatment with 2, which suggested that cell cyclin abnormity was involved in pancreatic tumor cell apoptosis." (PMID 36225350, 2022). "Akt/GSK3β phosphorylation and c-Myc and Cyclin D1 expression were assessed in pancreatic cancer cells." (PMID 35422475, 2022). "In this work, the result demonstrated that the expression level of Cyclin D1 was down-regulated by 2, suggesting that cell cyclin abnormity was involved in pancreatic tumor cell apoptosis." (PMID 36225350, 2022). "For instance, in pancreatic cancer cells, inhibition of cyclin D3 suppresses proliferation to a greater extent compared to cyclin D1 inhibition." (PMID 35406445, 2022). "The results of WB indicated that in the radioresistant pancreatic cancer cells, the cyclin D1, Bax, CDk4, cleaved caspase-3, Bcl-2, and γ-H2AX proteins were upregulated to varying degrees." (PMID 36276285, 2022). "C-myc and Cyclin D1, two downstream targets of Notch signaling, were increased in pancreatic cancer cells overexpressed with KLK8." (PMID 34395235, 2021). "In pancreatic cancer, Notch1 inhibits the expression of p21 and p27 by activating Cyclin D1 expression, and promotes tumor cell cycle." (PMID 33781318, 2021). "The overexpression of IRF2 increased the expressions of cyclin D1, consequently reduced apoptosis and contributed to cell growth in pancreatic cancer." (PMID 33735820, 2021). "For instance, in pancreatic cancer cells BxPc-3 and Panc-1, α-mangostin treatment induced a decrease of cyclin-D1 followed by cell cycle arrest at the G1 phase." (PMID 34885809, 2021). "ANP32E promotes the proliferation and migration of pancreatic cancer cells through up-regulation and activation of β-catenin/cyclin D1 signaling." (PMID 33148205, 2020). "Jungert revealed that Smad proteins and SP1 cooperatively regulate expression of a distinct set of TGF‐β target genes potentially involved in tumour progression, including MMP‐11, cyclin D1 and Smad7 in pancreatic cancer cells." (PMID 32729205, 2020). "RSV effectively suppressed the growth of pancreatic cancer (PaCa) in an orthotopic mouse model through the downregulation of NF-κB, cyclin D1, COX-2, intercellular adhesion molecule-1 (ICAM-1), matrix metallopeptidase-9 (MMP-9), and survivin." (PMID 32244860, 2020). "According to another previous study, CCND1 and Bcl-2 concentrations are closely related to unfavorable prognosis and low survival rate of patients with pancreatic cancer." (PMID 31718693, 2019). "Regulated directly by miR‐720, cyclin D1 played a promoting role in both cellular proliferation and metastasis in pancreatic cancer." (PMID 30974047, 2019). "Mechanistically, KLF5 promoted expression of E2F1, cyclin D1 and Rad51, while inhibiting expression of p16 in pancreatic cancer cells." (PMID 31327760, 2019). "This function of cyclin D1 suggests its potential involvement in the regulation of cell cycle progression in pancreatic cancer." (PMID 31327760, 2019). "Cyclin D1 is known to function as an oncogene in pancreatic cancer, usually being overexpressed in these tumors, hence anticancer agents that are able to reduce cyclin D1 levels are beneficial for the treatment of pancreatic cancer." (PMID 33912613, 2018). "Meanwhile, the down-regulated transforming growth factor beta receptor II (TGFBR2) and CCND1 were significantly enriched in both the pathways of chronic myeloid leukemia (p = 9.85E−03) and pancreatic cancer (p = 4.69E−02)." (PMID 27716259, 2016).